GLI2 (GLI family zinc finger 2)
Diseases named in the same sentence as GLI2 in open-access papers (continued):
Sharing a sentence is not in itself a finding about the gene and the disease.
achondroplasia (1 paper, 2020). Achondroplasia is the most common form of chondrodysplasia, characterized by rhizomelia, exaggerated lumbar lordosis, brachydactyly, and macrocephaly with frontal bossing and midface hypoplasia. "For example, mutations in ACVR1, FGFR3, PTHrP, and GLI2 genes result in fibrodysplasia ossificans progressive (FOP), achondroplasia (ACH), brachydactyly type E2, and Culler–Jones syndrome, respectively." (PMID 32079226, 2020).
adrenal hypoplasia (1 paper, 2023). "We performed gene expression, cellular analyses, and reporter assays to demonstrate that DAX1 (dosage-sensitive sex reversal adrenal hypoplasia congenital critical region on X chromosome, gene 1) interacts with GLI1 and GLI2, the master regulators of Hh signaling." (PMID 37504255, 2023).
AIDS (1 paper, 2012). A syndrome resulting from the acquired deficiency of cellular immunity caused by the human immunodeficiency virus (HIV). "This newly identified mechanism GLI2-mediated TGF-β1 regulation may have implications in diseases such as cancer and AIDS, where high levels of TGF-β1 contribute to pathogenesis." (PMID 22859956, 2012).
ameloblastoma (1 paper, 2013). The most common odontogenic tumor, arising from the epithelial component of the embryonic tooth and usually affecting the molar-ramus region of the mandible or maxilla. "We detected expression of SHH, patched, GLI1, GLI2 and GLI3 in the ameloblastoma specimens and AM-1 cells." (PMID 23835807, 2013). "In the present study, we examined the expression of SHH, PTCH, GLI1, GLI2, and GLI3 in ameloblastoma and investigated their functions using an ameloblastoma cell line." (PMID 23835807, 2013). "In ameloblastoma, immunoreactivity for SHH, PTCH, GLI1, GLI2 and GLI3 was seen in almost all tumor cells, but not in the stromal cells." (PMID 23835807, 2013).
Anxiety (1 paper, 2026). Intense feelings of nervousness, tension, or panic often arise in response to interpersonal stresses. "Female double heterozygote Gli2+/-; Gli3+/699 mice showed reduced social behavior and increased anxiety-like behaviors." (PMID 42219751, 2026). "Gli2+/- mice exhibited sex-specific changes in anxiety-like behaviors." (PMID 42219751, 2026).
Ataxia (1 paper, 2023). Ataxia refers to impaired coordination of voluntary muscle movement.
benign prostate hyperplasia (1 paper, 2018). "A previous study has found that the expression of GLI2 was significantly higher in PC than in benign prostate hyperplasia, decreased after androgen ablation in a limited time window but became highly expressed again in CRPC." (PMID 30513511, 2018).
cartilage tumor (1 paper, 2019). "Our identification of potential target genes that are unique and common to GLI1 and GLI2 in neoplastic chondrocytes contributes to elucidating potential pathways through which Hh signaling impacts cartilage tumor biology." (PMID 30695055, 2019).
cholangiocarcinoma (1 paper, 2021). A carcinoma that arises from the intrahepatic biliary tree (intrahepatic cholangiocarcinoma) or from the junction, or adjacent to the junction, of the right and left hepatic ducts (hilar cholangiocarcinoma). "Altogether, the reported studies provide a role for the Hedgehog-GLI signaling pathway, particularly for GLI1 and GLI2, as reliable prognostic factor for cholangiocarcinoma." (PMID 34638259, 2021). "Both mutation and copy number alterations (CNA) affecting Hedgehog pathway main members, namely GLI1, GLI2, GLI3, SMO, PTCH1/2, SUFU, and DHH, have been observed in mixed cholangiocarcinoma patients with different frequencies." (PMID 34638259, 2021).
choriocarcinoma (1 paper, 2014). An aggressive malignant tumor arising from trophoblastic cells. "Downregulation of Gli1, Gli2, Gli3 and Kif7 was demonstrated in clinical samples of choriocarcinoma and hydatidiform moles as well as choriocarcinoma cell lines when compared with normal placentas." (PMID 25265279, 2014).
colorectal tumor (1 paper, 2023). "Co-culture experiments show that GLI2- decreased colorectal tumor cells lead to down-regulation of TIM-3 and PD1 in NK cells, which are restored by TGF-bate active protein powder." (PMID 38159250, 2023). "Besides, the Elisa assay shows that GLI2-decreased colorectal tumor cells lead to up-regulation of IFN-gamma in NK cells." (PMID 38159250, 2023).
Coma (1 paper, 2021). The complete absence of wakefulness and consciousness, which is evident through a lack of response to any form of external stimuli. "Interestingly, we observed a significant increase in the general activity in COMA patient–derived fibroblasts compared with control cells resulting in higher basal expression levels of GLI1, GLI2, GLI3, and PTCH1." (PMID 33024317, 2021).
diaphragmatic hernia (1 paper, 2022). A congenital or acquired weakness or opening in the diaphragm which allows abdominal contents to protrude into the chest cavity; congenital diaphragmatic hernias are caused when the embryonic diaphragm fails to fuse. "Another report in murine models described an association between Gli3−/− mutants and omphalocele, whereas left-sided congenital diaphragmatic hernia was observed in Gli3, Gli2 and in a Gli2/Gli3 double mutant." (PMID 35885957, 2022).
Down syndrome (1 paper, 2018). "Indeed, aberrant DNA methylation in the GLI2 gene and other HH pathway members has been studied in relation to developmental disorders (including pre-eclampsia and Down syndrome) and cancer." (PMID 29682088, 2018).
E. coli infection (1 paper, 2021). "Here, we subsequently demonstrated that meningitic E. coli infection could subvert this intercellular communication within BBB by attenuating TGFBRII/Gli2-mediated such signaling." (PMID 34281571, 2021).
Ectrodactyly (1 paper, 2024). A condition in which middle parts of the hands and/or feet (digits and meta-carpals and -tarsals) are missing giving a cleft appearance. "Two variants with damaging PolyPhen and SIFT predictions were found in genes of the SHH pathway: rs2592595, associated with ectrodactyly, and rs11573590, found in GLI2 and PTCH3, respectively." (PMID 38785976, 2024).
embryonal carcinoma (1 paper, 2011). A non-seminomatous malignant germ cell tumor characterized by the presence of large germ cells with abundant cytoplasm resembling epithelial cells, geographic necrosis, high mitotic activity, and pseudoglandular and pseudopapillary structures formation. "To study the molecular basis of neurogenic properties of Gli2, we used a well-established embryonic stem cell model, the P19 embryonal carcinoma (EC) cell line, which can be induced to differentiate into neurons in the presence of retinoic acid (RA)." (PMID 21559470, 2011).
Epstein-Barr virus infection (1 paper, 2022). An infection that is caused by Epstein-Barr virus. "Finally, four significant KEGG enrichment pathways were identified (P < 0.05): beta-Alanine metabolism (SMOX, HIBCH), Pathways in cancer (GLI2, AR, TXNRD3, TRAF3, FGF16), Non-homologous end-joining (MRE11), Epstein-Barr virus infection (TRAF3, PSMD13, SIN3A)." (PMID 36330154, 2022). "Finally, the results of KEGG enrichment analysis showed four significantly enriched pathways (P < 0.05): beta-Alanine metabolism (SMOX, HIBCH), Pathways in cancer (GLI2, AR, TXNRD3, TRAF3, FGF16), Non-homologous end-joining (MRE11), Epstein-Barr virus infection (TRAF3, PSMD13, SIN3A)." (PMID 36330154, 2022).
Esophageal atresia (1 paper, 2013). A developmental defect resulting in complete obliteration of the lumen of the esophagus such that the esophagus ends in a blind pouch rather than connecting to the stomach. "Gli2–/–,Gli3+/– mutants displayed esophageal atresia with tracheo-esophageal fistula and a severe lung phenotype." (PMID 24274029, 2013).
esophageal cancer (1 paper, 2024). A primary or metastatic malignant neoplasm involving the esophagus. "Moreover, GLI2 has been identified as a potent oncogene in esophageal cancer, including ESCC, and it is present at high levels in these diseases." (PMID 38924029, 2024).
Ewing sarcoma (1 paper, 2011). A small round cell tumor that lacks morphologic, immunohistochemical, and electron microscopic evidence of neuroectodermal differentiation. "Furthermore, activation of Gli1 (a Gli2 transcriptional target) seems to be a major downstream effector of the EWS-FLI1 oncoprotein which drives another SRBC tumor, Ewing Sarcoma." (PMID 22039523, 2011).
fibrosis (1 paper, 2025). the formation of excess fibrous connective tissue in an organ or tissue in a reparative or reactive process. "Furthermore, in cerulein-induced CP model, Gli2ΔPSC mice displayed markedly reduced pancreatic fibrosis compared to Gli2fl/fl controls, highlighting the functional importance of GLI2 in driving pancreatic fibrogenesis in vivo." (PMID 41281756, 2025). "In the present study, we observed that pancreatic fibrosis was not alleviated in SmoΔPSC mice compared to Smofl/fl controls following CP induction, with PSCs from SmoΔPSC mice still showing high GLI2 expression." (PMID 41281756, 2025).
fluorosis (1 paper, 2021). "In addition, in the present study, real-time PCR revealed that the relative expressions of Ihh, Gli2, and Smo were increased in osteoblasts exposed to fluoride, and the mRNA and protein expressions of Ihh, Gli2, and Smo were also upregulated in the bone tissue of rats with fluorosis." (PMID 33637095, 2021).
folate deficiency (1 paper, 2022). A nutritional condition produced by a deficiency of FOLIC ACID in the diet. "HMeDIP-PCR revealed that binding of these Shh-related genes (Gli2, Hhatl, Smurf1, and Gsnk1g3) to 5hmC was significantly increased upon folate deficiency." (PMID 36199572, 2022).
gallbladder cancer (1 paper, 2024). "For example, GLI2 participates in the enhanced invasive ability of gallbladder cancer cells by increasing cell EMT." (PMID 38924029, 2024). "The activation and aberrant expression of GLI2 have been reported to induce the malignant phenotypes of multiple cancers, such as castration-resistant prostate cancer, renal cell carcinoma and gallbladder cancer." (PMID 38924029, 2024).
hair disorder (1 paper, 2022). "In addition, the hair disorder– associated genes (i.e. Gli2)." (PMID 35672687, 2022).
head and neck squamous cell carcinoma (1 paper, 2016). A squamous cell carcinoma that arises from any of the following anatomic sites: lip and oral cavity, nasal cavity, paranasal sinuses, pharynx, larynx, and salivary glands. "Nevertheless, a recent study has shown that overexpression of survivin, which is a classical transcriptional target of Gli-2, was associated with radiosensitivity and improved survival in patients with head and neck squamous cell carcinoma." (PMID 27918595, 2016).
hemangioma (1 paper, 2013). A benign vascular lesion characterized by the formation of capillary-sized or cavernous vascular channels. "Gli2 expression in NLT from hemangiomas and PLT were negative or weakly positive, and mainly moderately or strongly positive in HCC." (PMID 23356443, 2013).
Hepatitis (1 paper, 2016). Inflammation of the liver. "Additionally, we found that the expression of Gli2, FoxM1 and KIF20A is significantly correlated with HBV-caused hepatitis, positive vascular invasion, poor histologic grade and TNM stage." (PMID 27036048, 2016).
HIV-1 infection (1 paper, 2012). The type species of lentivirus and the etiologic agent of acquired immunodeficiency syndrome (AIDS). "The binding of HIV-1 Tat to GLI2 suggests a potential mechanism for TGF-β1 induction in HIV-1 infection." (PMID 22859956, 2012).
house dust mite allergy (1 paper, 2018). "Although the numbers per group were quite low to perform robust statistical analysis, we observed that hypermethylation of the GLI2 DMR was mainly associated with rhinitis in the FLEHS1 cohort and with house dust mite allergy in the FLEHS2 cohort." (PMID 29682088, 2018).
hydrolethalus syndrome (1 paper, 2020). Hydrolethalus (HLS) is a severe fetal malformation syndrome characterized by craniofacial dysmorphic features, central nervous system, cardiac, respiratory tract and limb abnormalities. "These include Pallister‐Hall syndrome (PHS), as well as HPE9 and Culler‐Jones syndrome (CJS), due to dominant mutations in the GLI3 and GLI2 genes, respectively, and hydrolethalus syndrome related to recessive mutations in HYLS1 and KIF7." (PMID 31840946, 2020).
Infertility (1 paper, 2016). "Male Gli2+/–;Gli3Δ699/+ mice displayed several genital and gonadal defects, which could all contribute to infertility." (PMID 27814383, 2016).
insulin-dependent diabetes (1 paper, 2024). "Here, we apply CRISPR-Cas9 gene editing on human iPSCs to study a heterozygous missense variant in GLI2 identified in two siblings with early-onset and insulin-dependent diabetes of unknown cause." (PMID 38509065, 2024).
jaw cysts (1 paper, 2013). "Gli1 is another well-defined hedgehog signaling effector, but there is no report on occurrence of jaw cysts in Gli1 transgenic mice, suggesting that GLI2 is more essential than GLI1 in KCOT development." (PMID 23951062, 2013).
kidney cancer (1 paper, 2021). Primary or metastatic malignant neoplasm involving the kidney. "Interestingly, DAXX has also been associated with degradation of Gli2 and PTEN in kidney cancer." (PMID 34680332, 2021).
kidney papillary carcinoma (1 paper, 2020). "Noticeably, in bladder, colorectal and kidney papillary carcinoma, GLI2 (and GLI1) expression shared bad prognostic value with that of TGFB genes, while high HH expression was associated with a positive outcome." (PMID 32879407, 2020).
kidney tumor (1 paper, 2011). "In two tumor types that have not previously been found in somatic mutagenesis screens, we used common insertion site analysis to identify Mitf as a driver in kidney tumor formation and truncated Gli2 as a driver of SRBC tumors." (PMID 22039523, 2011).
large cell carcinoma (1 paper, 2013). A malignant epithelial neoplasm composed of large, atypical cells. "In H520 squamous lung carcinoma cells and in large cell carcinoma cells (data not shown), the specific silencing of Gli1, Gli2 or Gli3 had a similar effect in cell proliferation and cyclin expression." (PMID 23667589, 2013).
leukoplakia (1 paper, 2024). A white patch or plaque on a mucous membrane that cannot be characterized clinically or pathologically as any other disease. "Furthermore, comparing epithelial cell clusters revealed that GLI2 expression was significantly upregulated in a higher proportion of epithelial cells in leukoplakia tissue compared to normal tissue." (PMID 38976559, 2024). "To further characterize the GLI2‐expressing epithelial cells in leukoplakia, we re‐analyzed the gene profiles of epithelial cells based on GLI2 expression and identified 5491 upregulated and 1153 downregulated genes in GLI2‐expressing cells compared to cells without GLI2 expression (p < 0.05)." (PMID 38976559, 2024).
Li-Fraumeni syndrome (1 paper, 2016). "Multiple amplicons in a SHH setting usually associate GLI2 with MYCN and may indicate Li-Fraumeni syndrome, which is linked to a dismal prognosis." (PMID 26857864, 2016).
liposarcoma (1 paper, 2023). A usually painless malignant tumor that arises from adipose tissue. "Future work on this project will directly target Gli2 in syngeneic murine liposarcoma models to determine if Gli2-mediated Hedgehog signaling contributes to intrinsic tumor dedifferentiation and stemness or immune exclusion." (PMID 37444470, 2023). "The previous results provided rationale that Gli2 may contribute a larger role in the state of dedifferentiation for liposarcoma tumors than Gli1." (PMID 37444470, 2023). "Taken together, these results suggested that Gli2 activity could indeed vary based on the degree of differentiation with liposarcoma tumors, albeit a limited conclusion due to lack of robust tumor sequencing data at this time." (PMID 37444470, 2023).
mandibular hypoplasia (1 paper, 2025). "Mutations in Gli2, a downstream component of the Hh pathway, has been linked to human mandibular hypoplasia, while mouse Gli2 knockouts led to disc defects, similar to those observed in Ihh mutants." (PMID 41103044, 2025).
mastitis (1 paper, 2022). Inflammation of breast tissue during lactation or postpartum due to an obstructed duct or infection. "For example, the GLI2 gene was identified as a candidate gene for the Chronic subclinical mastitis trait in dairy cows, a disease that, when it occurs, can reduce milk production or lead to culling of cows." (PMID 36330154, 2022).
meningitis (1 paper, 2021). A disorder characterized by acute inflammation of the meninges of the brain and/or spinal cord. "Since Gli2 as well as the gene promotor activity in hBMECs was observed to be significantly decreased by meningitis E. coli RS218, we therefore transfected the pGL3-gli2-promo-WT reporter plasmid into HEK-293 T cells, and preliminarily tested the regulative effect of RS218 on Gli2 transcription." (PMID 34281571, 2021).
mesenchymal tumor (1 paper, 2016). "Given that the Hedgehog pathway has been shown to control the development of the mouse gut mesenchyme, we sought to determine whether two commonly studied murine models of the mesenchymal tumor GIST express key Hedgehog signaling components (Shh, Ihh, Ptch1, Smo, Gli1, Gli2, Gli3)." (PMID 27793025, 2016).
mesothelioma (1 paper, 2015). A usually malignant and aggressive neoplasm of the mesothelium which is often associated with exposure to asbestos. "Targeting the Hh pathway either through RNA-interference knockdown of GLI1 and GLI2 or using Gli inhibitors, has been shown to induce growth inhibition and cell death in mesothelioma cells and xenograft tumors in vivo." (PMID 25544756, 2015).
metastatic tumours (1 paper, 2011). "Less equivocal is the role of GLI in advanced PCa: high levels of GLI1 mRNA have beendescribed in metastatic tumours and both GLI1 and GLI2 have been linked withandrogen-independence." (PMID 21633508, 2011).
olfactory neuroblastoma (1 paper, 2024). An olfactory neuroblastoma arising in the paranasal sinus. "Olfactory neuroblastoma (ONB), another rare tumor of the epithelium in the nasal cavity, also showed activation of the Hedgehog pathway (IHC staining of PTCH1, GLI1, and GLI2), as well as inhibition by Hedgehog pathway inhibitor cyclopamine in vitro on two ONB cell lines." (PMID 38731849, 2024).
omphalocele (1 paper, 2022). Omphalocele is an embryopathy classified in the group of abdominal celosomias and is characterized by a large hernia of the abdominal wall, centered on the umbilical cord, in which the protruding viscera are protected by a sac. "We found a patient presenting omphalocele and a microdeletion in 2q14.2q14.3 encompassing the GLI2 locus, a gene of the hedgehog signaling pathway." (PMID 35885957, 2022). "Taking all these results together, we propose that the absence of GLI2 may be related to the omphalocele exhibited by the patient." (PMID 35885957, 2022).
osteoarthritis (1 paper, 2023). A noninflammatory degenerative joint disease occurring chiefly in older persons, characterized by degeneration of the articular cartilage, hypertrophy of bone at the margins and changes in the synovial membrane. "MiR-1 can delay the progression of osteoarthritis by inhibiting IHH and IHH regulates RUNX2 through GLI2 to stimulate osteoblast differentiation." (PMID 36766336, 2023).